LEP (leptin)
Diseases named in the same sentence as LEP in open-access papers (continued):
Sharing a sentence is not in itself a finding about the gene and the disease.
diabetes (continued). "Leptin and adiponectin, because of their significant role in the regulation of lipid and carbohydrate metabolism, are the two adipokines that have been extensively studied in vitro and in vivo in animals and in human subjects with type 1 (T1DM) and type 2 diabetes mellitus (T2DM)." (PMID 24072088, 2013). "Our observation that leptin was an independent determinant of HOMA-IR in girls, but not in boys, is however in line with the notion that, in adulthood, inflammation appears more strongly associated with IR and diabetes risk in females than in males." (PMID 21365005, 2011). "However, transplantation of ob/ob adipose tissue (which does not produce leptin) in lipodystrophic rats does not reverse diabetes nor is it beneficial to inject leptin in obese humans with leptin resistance." (PMID 15530168, 2004). "Determinants of the “low leptin/IGF-1/HbA1c” biomarker status included younger age, lower BMI, and prolonged breast-feeding duration; but particularly several parental characteristics revealed strong association such as no family history of diabetes and hypertension, and lower maternal BMI." (PMID 39899498, 2025). "In addition, some studies have suggested that the adiponectin-leptin ratio (ALR) may be an effective parameter for the assessment of IR in individuals with or without diabetes." (PMID 29694637, 2018). "A previous study among patients with diabetes reported an association between BCAA levels and adipokines; however, it only reported the inverse association between BCAA and adiponectin concentrations, but did not report a significant correlation between BCAA and leptin levels." (PMID 29348480, 2018). "Our objective was to compare plasma adiponectin, leptin, leptin/adiponectin ratio (LAR) and hs-CRP in obese non-diabetic subjects and non-obese Type 2 DM patients, as well as determining the association of these adipokines with MetS and diabetes-related quantitative traits." (PMID 25276234, 2014). "In addition, leptin, at concentrations similar to those found in the plasma of diabetic patients, stimulates the release of active macrophage LPL through an oxidative stress-dependent pathway suggesting a proatherogenic effect of leptin on macrophages in diabetes." (PMID 25143800, 2014). "A limitation of our study is that although subjects were obese, they were not hyperglycemic or insulin resistant as evaluated by HOMA-IR; thus, results may not be indicative of results that might be obtained using leptin therapy in a population with glucose intolerance or before diabetes." (PMID 24987413, 2014). "Subgroup analyses revealed a significant leptin-lowering effect in placebo-controlled studies (SMD: −0.22; 95% CI: −0.43, −0.01, p = 0.04), but not in diabetes medications-controlled studies (SMD: −0.17; 95% CI: −0.43, 0.08, p = 0.17)." (PMID 36467062, 2022). "However, there is conflicting information whether leptin is a marker for CVD in diabetes or not." (PMID 33925808, 2021). "In our current study, plasma leptin level was comparable between diabetic and non-diabetic patients even though BMI, VFA and SFA are significant higher in diabetes." (PMID 26338087, 2015). "In the present study, we examined the mutual relationships among plasma leptin, HRV, and visceral fat volume in 100 patients with diabetes, as well as 100 age- and gender-matched non-diabetic patients with cardiovascular risk factors." (PMID 26338087, 2015). "In contrast, BMI, LDL, waist circumference, CRP, leptin, A-FABP and RBP-4 did not differentiate the types of diabetes." (PMID 22164267, 2011). "There will be little or no possibility for leptin to induce adipogenesis and recover subcutaneous WAT in these cases, since either the major adipogenic pathways are primarily absent or inhibited by the treatment for diabetes." (PMID 31920961, 2019).
diabetes (continued). "Unlike that of leptin and LAR, serum hs-CRP levels were higher in non-obese Type 2 DM than that in obese subject, which is concordant with several cross-sectional studies showing an increase of CRP levels in patients with diabetes." (PMID 25276234, 2014). "The MD in leptin levels was then evaluated in each subgroup: the patients with ACS versus the controls, the patients with ACS versus the patients with stable angina pectoris (SAP), and the patients with type 2 diabetes mellitus (T2DM) and ACS versus the patients without diabetes, but with ACS." (PMID 40362168, 2025). "Interestingly, icv leptin administration also normalizes excessive glucagon secretion and HPA axis activity in uncontrolled diabetes, whereas icv FGF1 injection does not — and yet, both appear to inhibit AgRP neurons, activate POMC neurons, and thereby increase net melanocortin signaling." (PMID 40371641, 2025). "In humans, compared to the NOND group, the diabetes (obese or nonobese) groups exhibited negative correlations between adiponectin and IL-2 and IL-23, while showing positive correlations with ENA78, eotaxin, and IP-10, along with positive correlations between leptin and insulin and IL-23." (PMID 39474247, 2024). "Glucose, leptin, and ghrelin levels could not consequently be measured after fasting due to logistic limitations in CMRI planning (mostly at the end of the day) and patient comorbidity like diabetes." (PMID 32198618, 2020). "Interestingly, subcutaneous transplantation of embryonic BAT can ameliorate STZ-induced diabetes, suggesting that BAT may play a key role in the regulation of glucose metabolism brought on by leptin in the absence of insulin." (PMID 25870537, 2015). "Thus, despite diabetes-induced migratory defect, db/db mice could mobilize cells in response to G-CSF or AMD3100 but not in STZ-diabetic mice, which further supports the notion that lack of inhibitory signal from leptin-Lepr signaling preserves or even augments mobilization." (PMID 27188595, 2016).
metabolic syndrome (933 papers, 2004 to 2026). A cluster of metabolic risk factors for CARDIOVASCULAR DISEASES and TYPE 2 DIABETES MELLITUS. "This was not due to the mice becoming “lean”, but rather because of an authentic lipodystrophy, a condition due to a metabolic syndrome typically associated to decreased levels of leptin, insulin-resistant diabetes, hyperlipidemia and steatosis." (PMID 39327506, 2025). "Deficiencies in PPARγ and leptin are associated with metabolic syndrome, characterized by dyslipidemia, renal hypertrophy, and elevated levels of the profibrotic cytokine transforming growth factor beta (TGFβ) in the kidneys." (PMID 40149950, 2025). "It has been shown that the adiponectin/leptin (AL) ratio is a better diagnostic marker for classifying subjects with metabolic syndrome than leptin or adiponectin alone." (PMID 41227378, 2025). "Children with a higher BMI z-score had a higher risk of being in the “inflammation” and “dyslipidemia/high leptin” status and a lower chance of being in the “low leptin/IGF-1/HbA1c” status at age 8 with the effects again increasing with age." (PMID 39899498, 2025). "This study demonstrates that seasonal variation in PM2.5 exposure is associated with significant changes in insulin and leptin levels, with more pronounced responses among individuals with metabolic syndrome." (PMID 40863890, 2025). "Key risk factors, collectively referred to as metabolic syndrome, include dyslipidemia, leptin and adiponectin dysregulation, insulin resistance, impaired insulin secretion, and glucose intolerance." (PMID 41220421, 2025). "Serum leptin levels were linked to both cardiovascular risk and metabolic syndrome in the current investigation." (PMID 40255297, 2025). "The association of high leptin with low ghrelin was proposed as a stronger marker of early atherosclerosis than ghrelin alone in patients with metabolic syndrome." (PMID 40137085, 2025). "Leptin, a polypeptide hormone secreted by white adipose tissue, plays a role in immune responses and has been linked to dyslipidemia in LP." (PMID 40764478, 2025). "Children from families with low/medium education had a 55% [9%-119%] higher risk of being in the “dyslipidemia/high leptin” and 49% [1%-121%] higher risk of being in the “inflammation” status as compared to children in the “normal” status." (PMID 39899498, 2025). "Our data support this interpretation: higher leptin concentrations were associated with worse metabolic profiles, even after accounting for BMI and individual metabolic syndrome components." (PMID 40956476, 2025). "Although this study examined adipokines only at the transcriptional level and found no significant group differences, clinical evidence indicates that decreased leptin and increased resistin levels are associated with malnutrition and dyslipidemia." (PMID 41156533, 2025). "IP injection of Rec2 based liver-restricting leptin vector at doses as low as 1×109 vg per mouse was sufficient to rescue leptin deficiency and associated metabolic syndrome." (PMID 40709262, 2025). "This preclinical study demonstrates that V7-LEP via SQ administration at a low dose of 4×1010 vg per mouse completely normalized leptin deficiency and associated metabolic syndromes, supporting translational potential." (PMID 40709262, 2025). "Endogenously elevated leptin levels are associated with metabolic syndrome, abdominal obesity, and neuropathic pain mediated via microglial activation." (PMID 41180179, 2025). "Lower levels of adiponectin are associated with the onset of metabolic syndrome, whereas leptin, a hormone that plays a role in energy metabolism, shows a positive correlation with metabolic syndrome and abdominal obesity." (PMID 41561332, 2025). "Membership in a sports club decreased the risk of being in the “inflammation” (0.72 [0.53;0.98]) and “dyslipidemia/high leptin” (0.60 [0.44;0.83]) status." (PMID 39899498, 2025).
metabolic syndrome (continued). "Hyperleptinemia results in “leptin resistance” and is associated with adverse health outcomes such as coronary artery disease, IR, and metabolic syndrome." (PMID 38206766, 2024). "A study demonstrated that Hs treatment in rats with metabolic syndrome caused a reduction in body mass and intra-abdominal fat, as well as in triglycerides, insulin, and leptin levels in relation to the group with metabolic syndrome without treatment." (PMID 39504065, 2024). "Despite the importance and association of leptin with metabolic syndrome and its related disorders, there have been relatively fewer studies on serum leptin and its association with NAFLD." (PMID 38738048, 2024). "We found that individuals homozygous for a loss-of-function genetic variant in SMIM1 gene, underlying the blood group Vel, display excess body weight, dyslipidemia, altered leptin to adiponectin ratio, increased liver enzymes, and lower thyroid hormone levels." (PMID 38906141, 2024). "This study aims to ascertain the associations between serum leptin levels and metabolic syndrome and semen parameters in patients with infertility." (PMID 39496062, 2024). "Some authors consider that adiponectin and leptin, and consequently the L/A ratio, represent more accurate biomarkers for atherosclerosis than the traditional risk factors such as dyslipidemia, diabetes, or arterial hypertension." (PMID 39063610, 2024). "Ghrelin, Leptin, and Adiponectin secretion patterns present a mediating effect on the association between sleep duration, and metabolic syndrome." (PMID 39342373, 2024). "Results indicate that investigation of the combination of persistent neuroticism over time with elevated leptin as a risk factor for development of metabolic syndrome would be relevant for future research." (PMID 38773198, 2024). "A linear regression analysis was used to evaluate the association of adipokines and GGT with metabolic syndrome, demonstrating that 27% of the variance was explained by leptin, while adiponectin explained 10% of the model variance." (PMID 39771030, 2024). "High leptin levels and leptin resistance have been linked to pathological dysfunctions and metabolic syndromes." (PMID 36833129, 2023). "According to many studies, a substantial positive association exists between levels of leptin and metabolic syndrome." (PMID 37175603, 2023). "Ob/ob mice possess a mutation in the leptin gene, and as a result, ob/ob mice are hyperphagic, obese, and hyperglycemic and display dyslipidemia." (PMID 36904146, 2023). "Metabolic syndrome and chronic inflammation have an established association with increased adipocytokine (TNFα, IL-6, leptin, and chemerin) and decreased adiponectin levels." (PMID 37033655, 2023). "In the recessive model, the − 2548AA homozygous genotype of LEP carriers had an increased risk for the development of dyslipidemia (OR = 7.97, 95% CI = 2.17–29.36; p = 0.008)." (PMID 37978555, 2023). "Studies have shown that the metabolic syndrome is associated with a decrease in ghrelin and adiponectin levels and an increase in leptin levels." (PMID 36596839, 2023). "Development of Metabolic Syndrome (MetS) is strictly linked to pro-inflammatory action of adipocytes as a consequence of secretion of many factors including leptin and adiponectin as well as proinflammatory tumor-necrosis factor-alpha and interleukins." (PMID 36837434, 2023). "In an observational trial with a 14-year follow-up period, higher leptin levels were linked to an increased incidence of metabolic syndrome." (PMID 37238961, 2023). "Leptin and interleukin-1 beta (IL-1β) are two extensively studied biomarkers associated with metabolic syndrome (MetS) and osteoarthritis (OA)." (PMID 37703108, 2023). "Adiponectin can protect against HFD-induced glucose intolerance and dyslipidemia, and white adipose tissue-specific induction of adiponectin has been reported to rescue the diabetic phenotype of leptin-deficient ob/ob mice." (PMID 38069059, 2023).
metabolic syndrome (continued). "IGFBP2 is associated with multiple cardiovascular risk factors related to the metabolic syndrome and IR and is further regulated by LEP." (PMID 37329449, 2023). "Leptin has also been associated with cardiometabolic risk factors and has been proposed as a marker of metabolic syndrome, highlighting the importance of this factor." (PMID 37508717, 2023). "For type 2 diabetes, the genetically predisposed leptin-deficient ob/ob or leptin receptor-deficient db/db mice recapitulate well the human metabolic syndrome." (PMID 35883655, 2022). "We found that leptin mutation and mycobacterial infection lead to a similar metabolic syndrome in zebrafish larvae as well as in mice." (PMID 35933481, 2022). "Our results show that leptin mutations and mycobacterial infection lead to a similar metabolic syndrome." (PMID 35933481, 2022). "The stiff organ phenotype leads in the brain to glymphatic dysfunction following neurodegeneration (e.g. Alzheimer’s disease, Parkinson’s disease) and to gliosis of the mediobasal hypothalamus causing leptin-resistant dyslipidemia and T2D." (PMID 36151345, 2022). "Adiponectin and leptin levels are independently associated with the development of metabolic syndrome, diabetes mellitus type II, and cardiovascular diseases." (PMID 36558441, 2022). "In patients with metabolic syndrome, leptin is positively associated with somatic depressive symptoms but not total depressive symptoms." (PMID 35911226, 2022). "Although metabolic syndrome has variable definitions, abdominal obesity is an obligatory component; this provides rationale for leptin to be evaluated as a diagnostic tool." (PMID 35628271, 2022). "Higher leptin levels were associated with an increased incidence of metabolic syndrome both in an observational study with a 14-year follow-up period and in a study of schizophrenic patients." (PMID 35056647, 2022). "Leptin mutation leads to a similar metabolic syndrome as caused by mycobacterial infection in adult mice and larval zebrafish, characterized by the decrease of 11 amine metabolites." (PMID 35933481, 2022). "The results show that leptin mutation leads to a similar metabolic syndrome as caused by mycobacterial infection in the two species, characterized by the decrease of 11 amine metabolites." (PMID 35933481, 2022). "On the contrary, different genetic manipulations in mice, resulting in lower expression of either Bdnf or its TrkB receptor, cause hyperphagia and induce signs of metabolic syndrome including leptin and insulin resistance, dyslipidemia and hyperglycemia." (PMID 35242012, 2022). "The result showed that leptin mutation leads to a similar metabolic syndrome as caused by mycobacterial infection in the two species, characterized by the decrease of 11 amine metabolites." (PMID 35933481, 2022). "Both hormones, leptin and adiponectin, also contribute to the development of lipid metabolism disorders and represent a risk for fat-induced dyslipidemia." (PMID 36422195, 2022). "Previously, we have identified an association of genotypes and alleles of the rs3828942 of LEP with the development of metabolic syndrome in patients with schizophrenia receiving antipsychotic therapy." (PMID 36294794, 2022). "cmiRs-320 are inversely associated with several components of the metabolic syndrome and higher abundance of cmiR-320a-3p, typical of LD, predicts lower plasma leptin." (PMID 35733784, 2022). "Along the same line, another study found that levels of L/A had a stronger association with metabolic syndrome than either adiponectin or leptin separately, especially when controlled for BMI in Chinese youth." (PMID 36010082, 2022). "It was also reported that the predictive value of leptin for all-cause and CV death seems to be dependent on waist circumference, one of the criteria used to define metabolic syndrome." (PMID 36289903, 2022).